PPP1R37 (protein phosphatase 1 regulatory subunit 37)
Description:
Inhibits phosphatase activity of protein phosphatase 1 (PP1) complexes.
Synonyms: LRRC68
Tractability: PROTAC: its protein half-life has been measured.
Gene: Protein-coding gene on chromosome 19 (45,091,396 to 45,148,077, forward strand). Ensembl gene ENSG00000104866.
Subcellular location (Human Protein Atlas): Cytosol
Gene Ontology:
Molecular function: protein binding
Genetic constraint (gnomAD): Loss-of-function variants: 18 observed, 51.33 expected, observed/expected ratio (o/e) 0.35, 90% interval 0.24 to 0.52. The upper end of that interval is the gene's LOEUF score, 0.52, which puts it in group 2 of 6, group 1 being the genes least tolerant of losing a copy. Missense variants: 852 observed, 887.78 expected, observed/expected ratio (o/e) 0.96, 90% interval 0.91 to 1.02. Synonymous variants: 417 observed, 398.33 expected, observed/expected ratio (o/e) 1.05, 90% interval 0.96 to 1.13.
Homologues: Orthologues: chimpanzee PPP1R37 (99% identical), macaque PPP1R37 (98% identical), pig PPP1R37 (92% identical), dog PPP1R37 (90% identical), guinea pig PPP1R37 (90% identical), mouse Ppp1r37 (88% identical), rat Ppp1r37 (88% identical), zebrafish ppp1r37 (65% identical), tropical clawed frog ppp1r37 (60% identical), Caenorhabditis elegans F28C1.3 (34% identical), Drosophila melanogaster CG31635 (32% identical). Paralogues in human: CARMIL1 (22% identical), CARMIL3 (21% identical), CARMIL2 (20% identical), RNH1 (9% identical).
Diseases named in the same sentence as PPP1R37 in open-access papers:
PPP1R37 is named in the same sentence as 3 diseases in open-access papers, as found by Europe PMC text mining. Sharing a sentence is not in itself a finding about the gene and the disease. The quoted sentences say what the papers report.
Alzheimer disease (3 papers, 2023 to 2026). A progressive, neurodegenerative disease characterized by loss of function and death of nerve cells in several areas of the brain leading to loss of cognitive function such as memory and language. "An application to Alzheimer's disease also reveals cell-subtype-specific associations, including MS4A6A in the disease-associated microglial subtype and PPP1R37 in the inflammatory microglial subtype." (PMID 41820391, 2026). "An application to Alzheimer’s disease also revealed cell-subtype-specific associations, including MS4A6A in disease-associated microglia and PPP1R37 in both inflammatory microglial and astrocyte subtypes." (PMID 41256005, 2025). "Based on gene enrichment testing in FUMA, both MARK4 and PPP1R37 have been reported in “Alzheimer’s disease or HDL levels” in the GWAS catalog." (PMID 37391420, 2023). "Among the top 20 associated genes, the gene-set enrichment analysis showed that the GWAS catalog gene-set of Alzheimer’s disease or pleiotropy had 4 genes (GEMIN7, MARK4, PPP1R37, and NKPD1) overlapped (p = 1.74 × 10−7, adjusted-p = 3.16 × 10−4)." (PMID 37391420, 2023).
asthma (1 paper, 2025). "We found that higher genetically proxied expression of PPP1R37 is associated with lower levels of G-CSF/CSF-3, as well as with a lower risk of asthma." (PMID 39794498, 2025). "Using integrated results from our GWAS and TWAS findings, we identified an upstream mechanism of yet unknown relevance: higher PPP1R37 gene expression was associated with reduced G-CSF/CSF-3 levels and lower risk of asthma." (PMID 39794498, 2025).
depression (1 paper, 2023). "Given that the present study is a cross-sectional analysis of cortical physiology in LLD and there is no age-matched control group, we cannot assess whether the potential effects of MARK4 and PPP1R37 are related to depression, aging, or both." (PMID 37391420, 2023).